EPO (erythropoietin)
Diseases named in the same sentence as EPO in open-access papers (continued):
Sharing a sentence is not in itself a finding about the gene and the disease.
glioma (15 papers, 2014 to 2024). A benign or malignant brain and spinal cord tumor that arises from glial cells (astrocytes, oligodendrocytes, ependymal cells). "It has been reported that CDH5 and erythropoietin-producing human hepatocellular receptor A2 (EphA2) are highly expressed in VM-positive glioma compared with VM-negative glioma, and their expression is required for VM formation." (PMID 36294763, 2022). "The hypoxia-associated expression of erythropoietin and its receptor in cancer cells is also regulated by HIF-1, while erythropoietin signaling can contribute to the radioresistance of gliomas." (PMID 33806538, 2021). "Until now, controversial effects of EPO on glioma cells response to radiation or chemotherapy were reported." (PMID 25544764, 2015). "Recently, glioma-specific antigens assessed in preclinical studies have shown potential anti-glioma effects, such as epidermal growth factor receptor variant III (EGFRvIII), human epidermal growth factor receptor 2 (HER2), and erythropoietin-producing hepatocellular carcinoma A2 (EphA2)." (PMID 36768267, 2023). "The effect of EPO on the proliferation of the U251 Cell glioma line in the hypoxia model was explored, the expression changes in the transcriptome were screened by high-throughput sequencing technology, and the differentially expressed genes PI3K, IKKα, and CDK1 were verified." (PMID 35167649, 2022). "Additionally, MCs have been detected in increased numbers in the infiltrating zones of medulloblastomas and gliomas, while they were also found to be erythropoietin (EPO)-positive in 50 % of a series of hemangioblastoma specimens." (PMID 26377554, 2015). "Besides these studies with rHuEPO, our work represents the first investigation on the impact of the endogenous EPO/EPOR system present on glioma cells on the efficacy of radio- and chemotherapy." (PMID 25544764, 2015). "Recently, the presence of EPOR signaling and EPO-induced cellular proliferation was confirmed in renal cancer cells, head and neck squamous cell carcinomas, and cervical cancer cell lines, as well as glioma cells." (PMID 25426117, 2014). "Further investigations are needed to unravel whether GSC-derived soluble factor(s) trigger the EPO production in kidney to indirectly enhance the erythropoiesis and/or whether glioma microenvironment-derived EPO directly induces the erythropoiesis in BM and spleen." (PMID 36451253, 2022). "It has been recently reported that erythropoietin (EPO) and its receptor (EPOR) are involved in glioma growth." (PMID 25544764, 2015). "Recently, we and others have shown that erythropoietin (EPO), another major target gene of HIF activation, plays a role in tumour progression since GBM cells and glioma stem cells synthesise EPO and express its receptor." (PMID 25544764, 2015). "Moreover, enhanced EPO and EPOR expression with AKT signalization included resulted in the promotion of colon cancer cell growth, proliferation, and angiogenesis, and the same applies in the EPO-promoted proliferation of glioma cells in vitro and in vivo." (PMID 34299300, 2021).
iron overload (15 papers, 2010 to 2025). "Further investigation indicated that defective erythropoiesis is linked to impaired erythropoietin production in the kidney and subsequent iron overload." (PMID 39881295, 2025). "The associations of GDF15 and EPO levels with erythropoiesis markers and iron overload support their potential value in early identification of NTDT patients with a risk of EMH." (PMID 30834265, 2019). "Clinical evidence suggests that ineffective erythropoiesis associated with high circulating EPO levels efficiently downregulates HAMP expression even in the face of iron overload, since iron-overloaded patients with X-linked sideroblastic anemia continue to absorb iron." (PMID 30958854, 2019). "In fact, serum EPO levels in β−thalassemia patients with iron overload are higher than those in healthy people." (PMID 36620219, 2022). "The concentration of EPO in the severe iron overload group was significantly higher than that in the mild to moderate iron overload group and normal group(P<0.001)." (PMID 35680627, 2022). "Likewise, the administration of recombinant EPO was found to decrease iron overload in many tissues; particularly in the livers of patients with hereditary hemochromatosis." (PMID 36620219, 2022). "Although advances in erythropoietin therapy are expected to reduce iron overload in patients with CKD, iron overload is still prevalent, and is approximately 36% in the case of ESKD48,49." (PMID 36650247, 2023). "The aim of this study in NTDT patients was to establish relationships between the erythropoiesis biomarkers (GDF15, EPO, sTfR, and ERFE) and iron overload markers (SF, LIC, and hepcidin) with the severity as well as complications of EMH." (PMID 30834265, 2019).
multiple sclerosis (15 papers, 2008 to 2026). A progressive autoimmune disorder affecting the central nervous system resulting in demyelination. "EPO has been reported to support neuronal mitochondria and prevent memory impairment in animal models of multiple sclerosis, sleep deprivation, neurodegeneration, and brain injury." (PMID 34354241, 2021). "EAE is a classical model for multiple sclerosis, and in addition to specific anti-inflammatory effects, EPO and EPO derivatives are in this model believed to have beneficial effects due to antioxidative and other neuroprotective actions." (PMID 27990061, 2016). "In a previous report, administration of EPO has been shown to suppress the inflammatory response related to IFN-γ in an animal model of multiple sclerosis." (PMID 22383962, 2012). "In a mice model of multiple sclerosis, administration of EPO was reported to downregulate the inflammatory response, and in particular, suppress IFN-γ." (PMID 22383962, 2012). "In an experimental model of multiple sclerosis, an autoimmune disease of the CNS, administration of EPO inhibited the inflammatory response, delayed the onset of the disease, and decreased its severity." (PMID 22567318, 2012). "In experimental autoimmunencephalitis (EAE), an animal model for multiple sclerosis (MS), treatment with EPO and EPO analogs can improve functional recovery, reduce tissue damage, inflammatory responses and blood-brain barrier leakage." (PMID 20142991, 2009). "However, hypoxia has also been described as immune-independent pathomechanisms in multiple sclerosis, suggesting that both hypoxic and inflammatory pathways may independently regulate EPO alternative splicing into hS3 in the CNS." (PMID 41602576, 2026). "Consequently, EPO has been evaluated for the treatment of several diseases in the nervous system including neurodegenerative diseases like Parkinson's disease and multiple sclerosis and various types of ischemia including carbon monoxide poisoning, subarachnoid hemorrhage, and Friedreich's ataxia." (PMID 27990061, 2016). "Treatment with erythropoietin (Epo) in experimental autoimmune encephalomyelitis (EAE), the rodent model of multiple sclerosis (MS), has consistently been shown to ameliorate disease progression and improve overall outcome." (PMID 29029628, 2017). "In addition, EPO-mediated oligodendrogenesis and the inhibition of oligodendrocyte cytotoxicity, induced by inflammatory stimuli, could also contribute to the observed neuroprotection in experimental multiple sclerosis." (PMID 22567318, 2012). "Beneficial effects of short-term erythropoietin (EPO) therapy have been demonstrated in several animal models of acute neurologic injury, including experimental autoimmune encephalomyelitis (EAE)-the animal model of multiple sclerosis." (PMID 18382691, 2008).
periodontitis (15 papers, 2021 to 2025). An acute or chronic inflammatory process that affects the tissues that surround and support the teeth. "The abundant miR‐5107‐5p in EVs, following EPO stimulation, alleviates inflammatory bone loss in periodontitis mouse models through the EGFR/RhoA axis." (PMID 40289904, 2025). "Subsequently, we established a mouse periodontitis model to evaluate the therapeutic effects of EPO‐EVs on inflammatory bone loss in vivo." (PMID 40289904, 2025). "In summary, our findings demonstrate that EPO‐EVs, highly enriched with miR‐5107‐5p, partially mitigate inflammatory bone loss in periodontitis through the EGFR/RhoA axis, suggesting a potential therapeutic target for periodontitis treatment." (PMID 40289904, 2025). "EPO‐EVs restore the osteogenic function of mouse BMSCs (mBMSCs) and mitigate inflammatory bone loss in a periodontitis mouse model." (PMID 40289904, 2025). "A therapeutic strategy is proposed for periodontitis using extracellular vesicles derived from EPO‐stimulated macrophages (EPO‐EVs)." (PMID 40289904, 2025). "Collectively, these results suggest that EPO‐EVs/hydrogel effectively alleviated the destruction of alveolar bone in the experimental periodontitis mouse model." (PMID 40289904, 2025). "The representative IF images showed that OCN expression was reduced in the periodontitis (PD) model and significantly increased after 4‐week‐EPO‐EVs/hydrogel treatment." (PMID 40289904, 2025). "For the first time, we demonstrated that EPO‐EVs exert positive effects on bone regeneration within an inflammatory environment, as shown in both in vitro experiments and a mouse periodontitis model in vivo." (PMID 40289904, 2025). "This research intended to evaluate the efficacy of using EPO complementary with SRP in the treatment of periodontitis." (PMID 38406126, 2024). "Conversely, the administration of FK506/EPO mitigated the suppression of osteogenic differentiation in periodontitis, leading to a significant increase in the levels of osteogenic markers." (PMID 38239915, 2023). "An experimental study evaluating the treatment efficacy of EPO reported that EPO accelerated the early-healing rate of extraction sockets in mice with periodontitis." (PMID 37374263, 2023). "In order to assess the impact of FK506/EPO on osteogenic differentiation in rats with periodontitis, we utilized immunohistochemistry methods to measure the levels of osteogenic markers, namely, Collagen I, OCN, OPN, and RUNX2." (PMID 38239915, 2023). "To confirm these in vitro results in an in vivo condition, we evaluated the effects of EPO on bone formation using an in vivo mouse periodontitis model by examining the histomorphology and immunostaining." (PMID 36277197, 2022). "In this study, EPO was shown to increase the early healing rate of the extraction socket in mice with ligature-induced periodontitis." (PMID 36277197, 2022). "After the induction of periodontitis in the maxillary left second M, 10 IU/ml of EPO was locally applied to the extraction tooth sockets." (PMID 36277197, 2022). "Based on the in vitro examination, we evaluated the effect of EPO on bone formation using an experimentally-induced animal periodontitis model." (PMID 36277197, 2022). "As previously reported, EPO is a multifunctional cytokine with anti-inflammatory properties and is involved in regulating the regenerative capacity of bone formation from periodontitis." (PMID 36277197, 2022). "This study was aimed to investigate the efficacy of a topical erythropoietin for treatment of Stage III grade B/C periodontitis." (PMID 33957902, 2021). "The data demonstrate that the addition of mimic‐5107 or EPO‐EVs effectively targets EGFR and further enhances RhoA activity, thereby alleviating inflammatory bone loss in LPS‐induced mBMSCs and promoting alveolar bone development in periodontitis mouse models." (PMID 40289904, 2025).
periodontitis (continued). "To evaluate our hypothesis, we investigated the mimicking of EPOR-knockdown control PDLSCs to periodontitis patient-derived PDLSCs (PD-PDLSCs) and the successful rejuvenation of the dysfunction of PD-PDLSCs via EPO-EPOR signaling." (PMID 38509204, 2024). "This study is meaningful in that EPO can shorten the time taken for bone regeneration and promote the possibility of bone quality improvement for implant placement under conditions of periodontitis clinically, in the same way that it is used to treat fractures." (PMID 36277197, 2022). "However it is necessary to further examine the immunomodulation roles of EPO in the periodontitis in near future." (PMID 36277197, 2022). "To investigate whether miR‐5107‐5p suppresses EGFR expression and contributes to EPO‐EVs‐mediated bone regeneration under inflammatory conditions in vivo, we employed Antagomir‐5107 as miR‐5107‐5p specific inhibitor in the periodontitis mice model every 3 days after ligature removal." (PMID 40289904, 2025). "Above these data, it was speculated that EPO could preserve antiapoptosis, angiogenesis, and autophagy of PDLSCs under inflammatory microenvironment, which suggested its promising use for controlling periodontitis." (PMID 36199627, 2022). "In light of these observations, our study sought to evaluate the efficacy of CS in loading erythropoietin (EPO) and FK506 for the management of periodontitis." (PMID 38239915, 2023). "Local application of EPO gel in adjunct to SRP can improve clinical inflammation and CAL gain in periodontitis." (PMID 33957902, 2021). "Overall, EVs from EPO pretreated macrophages restore the osteogenic capacity of mBMSCs under inflammation by inhibiting EGFR expression, providing new insight into therapeutic mechanisms and offering a promising approach for future periodontitis treatment." (PMID 40289904, 2025). "However, treatment with FK506/EPO effectively suppressed the increase in serum TNF-α, IL-1β, and IL-6 induced by experimental periodontitis." (PMID 38239915, 2023). "We used erythropoietin (EPO), which has been reported to play an important role in bone healing and modulation of angiogenesis, as a therapeutic agent in vivo and in vitro experimental models to analyze its effect on periodontitis." (PMID 36277197, 2022). "So, we decided to evaluate the effects of local application of EPO on the clinical outcomes of non-surgical treatment of periodontitis." (PMID 33957902, 2021). "Given that EPO affects bone healing and angiogenesis, we examined the precise cellular effects of EPO in vitro using hPDLF and MC3T3-E1 cells, as well as its bone-healing capacity in vivo in tooth extraction sockets of a ligature-induced periodontitis mouse model." (PMID 36277197, 2022).
autoimmune disease (14 papers, 2011 to 2025). A disorder resulting from loss of function or tissue destruction of an organ or multiple organs, arising from humoral or cellular immune responses of the individual to their own tissue constituents. "In animal models of various autoimmune diseases, EPO reduced disease severity and was associated with decreased levels of proinflammatory cytokines." (PMID 33796104, 2021). "In various models of autoimmune diseases, EPO limits cell apoptosis and favors cell clearance, while reducing proinflammatory cytokines and promoting the induction of regulatory T cells." (PMID 33796104, 2021). "In summary, EPO derivatives are promising drugs in autoimmune diseases, allergies, organ IRI, and organ transplantation." (PMID 32015330, 2020). "Future studies are clearly warranted to unravel the potential of EPO as an interesting candidate in treating autoimmune diseases of the PNS." (PMID 22043313, 2011). "For example, in autoimmune diseases, EPO may alleviate excessive immune responses by regulating the balance of immune cells." (PMID 40191193, 2025). "Thus, we explored the anti-inflammatory and neuroprotective properties of EPO in autoimmune disorders of the PNS." (PMID 22043313, 2011). "EPO can also strongly suppress immune system activation and protect injured tissues from apoptosis, suggesting that it may be a promising therapeutic target in autoimmune diseases, allergy, and organ transplantation." (PMID 39474425, 2024). "Again, anti-EPO antibodies have been identified in human immunodeficiency virus/acquired immunodeficiency syndrome (HIV/AIDS) and autoimmune diseases like systemic lupus erythematosus." (PMID 36989322, 2023). "Again, anti-EPO antibodies have been identified in HIV/AIDS and autoimmune diseases such as systemic lupus erythematosus." (PMID 36989322, 2023). "Studies in patients with some autoimmune diseases and patients with HIV revealed high levels of anti-EPO antibodies." (PMID 32318578, 2020).
erythroleukemia (14 papers, 2008 to 2025). Acute erythroid leukemia characterised by the presence of at least 50% erythroid precursors and at least 20% myeloblasts in the bone marrow. "EPO had already been found to be activated by structural rearrangements in a mouse model of erythroleukemia, resulting in growth factor independence." (PMID 40162972, 2025). "The HCD-57 cell line is a mouse erythroleukemia cell line dependent on erythropoietin (EPO) for survival." (PMID 39652257, 2024). "In this study, we established stable cell lines with aberrant signaling resembling SHP2-mutant JMML through retroviral expression of SHP2-D61Y/E76K in HCD-57 cells, a murine erythroleukemia cell line that depends on erythropoietin (EPO) for survival." (PMID 36805832, 2023). "HCD57 cells, a murine erythropoietin (EPO)-dependent erythroleukemia cell line, were utilized to test the specificity of SCF-DM1." (PMID 35999600, 2022). "HCD-57 cells are murine erythroleukemia cells and require exogeneous erythropoietin (EPO) for survival." (PMID 33691697, 2021). "In a haematological model (erythroleukemia), IDH2 mutation caused methylation changes, which were successfully reversed by its inhibitor; similarly, it impaired the EPO-induced differentiation, which was restored upon mutant IDH2 inhibition." (PMID 27145078, 2016). "ELISA was used to evaluate EPO concentrations, and its biological activity was determined by proliferation of the EPO-sensitive human erythroleukemia cell line TF-1." (PMID 19014419, 2008). "Mouse erythroleukemia HCD57 cells are EPO-responsive and require EPO for survival." (PMID 36895793, 2023). "Each Db‐Fc was assessed by flow cytometry for binding to TF‐1 cells, which are derived from a human erythroleukemia, display endogenous EPOR, and only grow in the presence of either EPO, granulocyte‐macrophage colony‐stimulating factor (GMCSF), or interleukin 3 (IL‐3)." (PMID 40960423, 2025). "Aberrant EPO expression was also found in serially propagated FLV erythroleukemia cell lines, due to genomic rearrangements independent of retroviral integration." (PMID 33898929, 2021). "We provided compelling evidence that this feature was not an epiphenomenon occurring in chemically-induced, EPO-independent erythroleukemia cells, but a real cellular event that accompanies the late differentiation of MEL cells, and that of EPO-dependent primary erythroblasts as well." (PMID 23536862, 2013).
hypothyroidism (14 papers, 2016 to 2025). Abnormally low levels of thyroid hormone. "Hypothyroidism affects the process of erythropoiesis by inhibiting the release of erythropoietin from the kidney as it decreases gene expression." (PMID 38618448, 2024). "Other effects of hypothyroidism, such as decreased synthesis of erythropoietin and red blood cells and impaired systolic and diastolic functions of the heart, may also affect GFR." (PMID 39343908, 2024). "Hypothyroidism may lead to macrocytic anemia because of decreased bone marrow activity and decrease in erythropoietin secretion." (PMID 27316517, 2016). "Moreover, Hypothyroidism may have indirect effects on erythropoiesis by reducing gene expression and secretion of erythropoietin from the kidney." (PMID 40315206, 2025). "Second, certain potential confounders, such as hemoglobinopathies, hypothyroidism, and the use of iron supplements or erythropoietin, which can influence HbA1c levels, were not excluded." (PMID 40303646, 2025). "Although our patient's hemoglobin level was not affected by hypothyroidism, hypothyroid patients tend to use erythropoietin more than euthyroid patients." (PMID 36655149, 2023).